ERBB2 (erb-b2 receptor tyrosine kinase 2)
Diseases named in the same sentence as ERBB2 in open-access papers (continued):
Sharing a sentence is not in itself a finding about the gene and the disease.
lymph node metastasis (588 papers, 2005 to 2026). "The occurrence of ERBB2 amplification was also associated with a higher tumor grade and lymph node metastasis." (PMID 37173881, 2023). "This is interesting, as most data looking at ERBB2/HER2 status and clinical outcomes have shown that HER2 positivity is associated with high tumor grade, lymph node metastasis, and UC-specific mortality." (PMID 38136267, 2023). "Patients with ERBB2-positive GC were selected and the potential risk factors for lymph node metastasis and potential factors affecting prognosis were evaluated." (PMID 36059809, 2022). "Most studies demonstrate a poor prognosis for ERBB2-positive GC patients, particularly patients with associated clinical features such as serosa invasion, lymph node metastasis, and distant metastasis." (PMID 36059809, 2022). "ERBB-2 positivity has been shown as a high-risk factor for lymph node metastasis in patients with early GC." (PMID 36059809, 2022). "Therefore, we aimed to identify the risk factors for lymph node metastasis and prognostic factors of patients with ERBB2-positive GC." (PMID 36059809, 2022). "However, the factors associated with lymph node metastasis in ERBB2-positive GC patients are unknown." (PMID 36059809, 2022). "In this case, the genetic test results of the patient suggested ERBB2 gene amplification, which recurred in a short term after surgery, accompanied by multiple lymph node metastases and multiple bone metastases, which showed high aggressiveness." (PMID 39045556, 2024). "We also found that amplifications of KRAS and ERBB2 gene were present only in the lymph node metastasis and right middle lobe of P06, respectively." (PMID 34290355, 2022). "In this study, the rate of lymph node metastasis in ERBB-2 positive patients was 67.2% (82/122), which is significantly higher than that in ERBB-2 negative patients, which was 48.4% (346/714)." (PMID 36059809, 2022). "Lymph node metastasis of 3 (15.8%), 2 (10.5%) and 2 (10.5%) patients exhibited amplifications in all 3 exons of ERBB2, CCND1 and MYC, respectively." (PMID 33298978, 2020). "It was only possible to compare the IHC scores of the normal tissue adjacent to 1 mammary lymph node metastasis, which showed high protein scores for both antibodies (erbB-2 positive: MeL +++ and matching normal ++)." (PMID 24386251, 2013). "Of 41 patients with lymph node metastases, ERBB2 gene amplification was present in 24.4% (10/41) of the cases." (PMID 21689422, 2011). "In our search, 24.4% (10/41) and 34.1% (14/41) of patients with lymph node metastases harbored ERBB2 and EGFR gene amplification, respectively." (PMID 21689422, 2011). "In addition, we constructed a nomogram prognostic model of GC with lymph node metastasis and high expression of ERBB2." (PMID 34869310, 2021). "We found CNV in ERBB2 in DNA of primary tumor and lymph node metastasis." (PMID 33298978, 2020). "However, amplification of both ERBB2 and EGFR were significantly associated with the depth of invasion of the tumor and with lymph node metastasis." (PMID 21689422, 2011). "We also found significant correlation between ERBB2 mRNA and HER2 protein levels in brain metastasis (Spearman Cor = 0.697, P = 0.002), breast metastasis (Spearman Cor = 0.754, P = 0.002), lung metastasis (Cor = 0.882, P = 0.003), and lymph node metastasis (Spearman Cor = 0.410, P = 0.05)." (PMID 34051058, 2022). "In the high lymph-node metastasis (N2 and N3) group, SMAD2 expression was more frequent, as was ERBB2 and MET expression." (PMID 35650563, 2022). "In each case, only one (2.3%) patient had CNV in all 3 exons of CCND1 and ERBB2 in the corresponding primary tumor and serum, while 2 (4.7%) patients had CNV in all 3 exons of CCND1 in the corresponding primary tumor and lymph node metastasis." (PMID 33298978, 2020). "The 3-year survival rate of patients with ERBB2-positive lymph node metastasis was 48.2%, compared with 86.0% for those without lymph node metastasis (p < 0.001)." (PMID 36059809, 2022).
lymph node metastasis (continued). "We have established the best prognostic model of FAM83 family members in GC, including the prognostic model of patients with GC (FAM83C/D/G), patients with STAD with lymph node metastasis (FAM83C/D/G/H) and patients having STAD with high expression of ERBB2 (FAM83/G/H)." (PMID 34869310, 2021). "Besides, we have established the prognostic model of FAM83 family in STAD, including the prognostic model of STAD patients (FAM83C/D/G), STAD with lymph node metastasis (FAM83C/D/G/H) and STAD with ERBB2 high expression (FAM83G/H)." (PMID 34869310, 2021). "The third case (patient 63) had ERBB2 ampli fication in a lymph node metastasis that was not present in the corresponding bladder primary." (PMID 25886454, 2015). "Among patients with no lymph node metastases, those with ERBB2-amplified carcinomas had a trend for worse survival when compared with those without this genetic alteration (P=0.085)." (PMID 19156142, 2009).
colorectal cancer (577 papers, 2001 to 2026). A primary or metastatic malignant neoplasm that affects the colon or rectum. "Mutations in ERBB2 are found in ∼5% of patients with colorectal cancer, and some of these mutations can co-occur with ERBB2 amplification." (PMID 39790478, 2025). "Studies have shown that ERBB2 gene mutations in colorectal cancer occur most frequently in exon 21, followed by exons 19 and 20 (as in this study)." (PMID 39790478, 2025). "Data from two cohorts of patients with colorectal cancer with either ERBB2 amplifications or ERBB2 or ERBB3 mutations showed that treatment with pertuzumab plus trastuzumab had antitumor activity only in ERBB2 amplification." (PMID 41374970, 2025). "Although anti-HER2 therapy in patients with colorectal cancer harboring various ERBB2 gene mutations lacks sufficient evidence, some researchers think that recommending it as a treatment option is worth exploring." (PMID 39790478, 2025). "Research in colorectal cancer has revealed that PTPRO can associate with erb-b2 receptor tyrosine kinase 2 (ERBB2), thereby inhibiting signaling pathways and obstructing tumor growth." (PMID 38999976, 2024). "KRAS showed a decreased mutation frequency in colorectal cancer patients with ERBB2 amplification compared with non-ERBB2 amplification (15% vs. 49%)." (PMID 35911441, 2022). "In this regard, in a modern and large (1654 patients) primary colorectal cancer study, ERBB2 positivity (1.6%; 26 patients) was associated with advanced stages and a non-significant tendency towards worse OS." (PMID 35954382, 2022). "ERBB2-L755S is the most frequently altered codon and well-known driver oncogenic mutation observed in breast or colorectal cancer." (PMID 33863983, 2021). "In recent studies, it was observed that anti-ErbB2 targeted therapy can cause compensatory overexpression of ErbB3 in breast and colorectal cancers." (PMID 30621788, 2019). "The opportunity to target ERBB2/HER2 in colorectal cancer has recently emerged as it is amplified and/or mutated in 5% of CRC tumors, most often in KRAS WT tumors, which agrees with our data." (PMID 31805664, 2019). "A recent study found that ERBB2-mutant MSI colorectal cancer was susceptible to irreversible pan-HER inhibitors." (PMID 29296220, 2017). "Moreover, while ERBB2 alterations were largely amplifications in both gastric and colorectal cancers, ERBB2 point mutations were the most frequent type of alterations in SBA." (PMID 35267592, 2022). "Furthermore, we observed that ERBB2 is significantly mutated in colorectal cancer." (PMID 41413856, 2025). "Besides ERBB2, other genes encoding receptor tyrosine kinases or downstream proteins of their pathways are recurrently amplified, albeit in lower frequencies, in gastrointestinal cancers, such as gastric, esophageal, and colorectal carcinomas." (PMID 39768557, 2024). "ERBB2 kinase domain mutation occurs in human cancers such as gastric, breast, and colorectal cancers, and suggested that alterations of ERBB2-mediated signaling pathway by ERBB2 mutations alone or together with K-RAS mutations may contribute to the development of human cancers." (PMID 31477031, 2019). "Together, these findings suggest that specific metabolites produced by intestinal bacteria can activate critical targets such as NF-κB, PI3K/AKT, and ErbB2/ErbB3, thereby contributing to the development of colorectal cancer." (PMID 39948481, 2025). "TGF-B secretion by stromal cells enhances metastatic capacity in colorectal cancer, while in PDAC, it induces a myofibroblastic phenotype of cancer-associated fibroblasts via EGFR/ERBB2 signalling, promoting metastasis." (PMID 40826447, 2025). "Because of the high ORR of ERBB2-targeted therapy in salvage treatment for colorectal cancer, it is suggested to further explore and improve ERBB2-targeted therapy in future studies." (PMID 40051563, 2025).
colorectal cancer (continued). "To further demonstrate the generalizability of the novel engineered 3’UTR destabilization of ERBB2 oncogene, we extended this work into the NCIH2030 ERBB2-mutated non-small-cell lung cancer cell line and the HCT116 colorectal cancer cell line." (PMID 37359373, 2023). "The HERACLES trial was a phase II trial that investigated the combination of trastuzumab and lapatinib in 27 heavily pretreated colorectal cancer patients with ERBB2 amplification." (PMID 35565354, 2022). "Our earlier study has shown that ERBB2 mRNA and protein overexpression correlates with more aggressive colorectal cancer in the North African population." (PMID 36612126, 2022). "Recent trials have demonstrated promising results with HER2 directed therapy in ERBB2 amplified colorectal cancer." (PMID 35565354, 2022). "BRAFV600E, KRASG12C mutation, ERBB2 (HER2) amplification, and various receptor tyrosine kinase (RTK) fusions are rare but potentially therapeutically relevant in colorectal cancer (CRC)." (PMID 36700211, 2022). "In 68 patients with colorectal carcinoma (CRC), key driver mutations were detected as follows: KRAS, 40 (59%); NRAS, 1 (1%); BRAF, 4 (6%); ERBB2, 2 (3%); and ERBB3, 1 (1%)." (PMID 35323313, 2022). "Mutations and amplification of ERBB2 have also been reported in ~4% of NSCLC, 2–5% of colorectal cancers, 5–20% of biliary tract tumors, and in up to 60% of salivary duct carcinomas." (PMID 33946310, 2021). "Preliminary results have shown promising activity for the combination of trastuzumab with either lapatinib or pertuzumab in patients with heavily pretreated colorectal cancer with ERBB2 amplification." (PMID 33946310, 2021). "For instance, the overexpression of miR-32-5p contributed to radioresistance by targeting Transducer of ERBB2, 1 in colorectal cancer." (PMID 32219065, 2020). "ERBB2 copy number gains were also highest in gastric and colorectal cancers (median 4.8 and 6.6, respectively)." (PMID 31019892, 2019). "Overexpression or amplification of HER2 (ERBB2) occurs in several types of cancer including breast, ovarian, gastric and colorectal cancers." (PMID 29879129, 2018). "The most lethal on-target off-tumor toxicity reported in the literature is of a patient treated with ERBB2/HER2 specific third generation CAR T-cell for colorectal cancer." (PMID 30613448, 2018). "B1SP is a multi‐RTK pathway inhibitor targeting EGFR, MET, and HER2/ErbB2 and has potential clinical utility for a number of cancers wherein these RTKs are clinically validated targets including lung, breast, and colorectal cancers." (PMID 29348142, 2018). "It was reported recently that amplification of MET, FGFR1 and ERBB2 was involved in EGFR therapeutic resistance in colorectal cancer." (PMID 27738318, 2016). "A validation study was conducted in order to develop a validated ERBB2 scoring system for colorectal cancer with the aim of identifying ERBB2-positive patients suitable for enrollment in the HERACLES trial." (PMID 27542243, 2016). "The first fatal adverse event due to off-tumor recognition by a CAR occurred in a patient with colorectal cancer treated with high numbers of T cells expressing a third generation CAR targeting ERBB2/HER2." (PMID 27298832, 2016). "In the present study, we not only confirmed the over-expression of c-MET, ErbB2 and ErbB3 in human colorectal cancer, but also revealed the variation and complementary of these receptors." (PMID 24205104, 2013). "Taken together, our results show that colorectal cancer exhibits variation in oncogenic RTK due to different molecular patterns of expression including ErbB2/ErbB3/AKT and ErbB3/c-MET/MAPK." (PMID 24205104, 2013). "The partner of ErbB3 in the heterodimer, ErbB2, was also located mainly in the membrane of cancer cells and was similarly overexpressed in human colorectal cancer." (PMID 24205104, 2013).
colorectal cancer (continued). "By immunohistochemistry, we show here that RTK members ErbB2, ErbB3 and c-Met were in deed differentially overexpressed in colorectal cancer patient samples leading to constitutive activation of RTK signaling pathways." (PMID 24205104, 2013). "In the LARC population studied here, the observed frequencies of tumor aberrations of KRAS, BRAF, PIK3CA, and ERBB2 were in the order of magnitude previously reported in colorectal cancer." (PMID 23226389, 2012). "Additionally, pyrotinib combined with trastuzumab has shown antitumor activity in ERBB2 (HER2)-positive RAS/BRAF wild-type advanced colorectal cancer." (PMID 41413856, 2025). "Consequently, L. monocytogenes promotes the proliferation and migration of colorectal cancer cells by upregulating the expression of RTK family members ErbB2 and ErbB3, and inducing the tyrosine phosphorylation of Met." (PMID 39948481, 2025). "The second case involved a 41-year-old female with colorectal cancer and ErbB2 amplification (identified by FISH and NGS), who had previously received multiple lines of ErbB2-targeted therapies, including trastuzumab, pertuzumab, and a bispecific ErbB2 × 4-1BB agent." (PMID 39908697, 2025). "There is evidence that treatment of breast and colorectal cancers exhibiting ERBB2 amplification with ERBB2 targeted drugs such as trastuzumab and pertuzumab when used in combination with EGFR inhibitors may improve outcomes." (PMID 39678505, 2024). "However, we found that ERBB2 alterations were more prone to occur in younger patients with CRCs, which is an important finding given that incidence of younger patients with colorectal cancer have been increasing steadily." (PMID 39220126, 2024). "Furthermore, SMYD2-mediated regulation of the Erb-B2 receptor tyrosine kinase 2 (ERBB2)/fucosyltransferase 4 (FUT4) signaling pathway controls colorectal cancer growth." (PMID 39482529, 2024). "ERBB2/ERBB2 is overexpressed in many human cancers including breast, lung, and colorectal cancers." (PMID 37359373, 2023). "These miRNA were reported to be modulated in different cancers, namely, hsa-miR-505-5p (human cervical cancer), hsa-miR-1827; hsa-miR-650 (colorectal cancer), hsa-mir-3612; hsa-miR-940(cervical cancer), hsa–miR-4695-3p; hsa-miR-4763-3p; hsa-miR-3128 (ERBB2/Her2 gene)." (PMID 35965620, 2022). "The MyPathway trial, a phase IIA multiple basket study, also showed encouraging results with targeting ERBB2 amplification in heavily pretreated colorectal cancer patients: the combination of trastuzumab and pertuzumab was found to have a response rate of 37.5%." (PMID 35565354, 2022). "ERBB2 mutants might work as facilitated markers for prediction of high-risk SPs and might implicate a potential mechanism in the serrated pathway to colorectal carcinoma (CRC)." (PMID 35402217, 2022). "ERBB2 mutations are a frequent event in solid tumors, and the combination of trastuzumab and lapatinib has shown promising antitumoral effects in four different ERBB2-positive tumor entities as adenosarcoma, endometrial cancer, cholangiocarcinoma, and colorectal cancer." (PMID 34367146, 2021). "For example, no response to neratinib treatment was observed in BLCA and colorectal cancer patients with ERBB2 mutations in a clinical study." (PMID 33117683, 2020). "Interestingly, ErbB2 activation is present in about 5% of colorectal cancers developing resistance to EGFR-targeted therapies thus supporting investigation of anti-ErbB2 antibodies and related ADCs in these patients." (PMID 32039017, 2019). "High ERBB2 incidence and copy number gains were observed in gastric and colorectal cancer patients, often in the absence of other oncogenic mutations, underscoring its likely role as the driver alteration in those settings." (PMID 31019892, 2019). "The role of HER2/ERBB2 expression in colorectal cancer is very controversial." (PMID 27610130, 2016).